EFNB2 (ephrin B2)
Diseases named in the same sentence as EFNB2 in open-access papers (continued):
Sharing a sentence is not in itself a finding about the gene and the disease.
tumor (continued). "However, many reports suggested that the delay in tumor growth observed by ephrin-B2 targeted therapies might be dependent on angiogenesis inhibition in the tumor." (PMID 29190834, 2017). "Indeed, EFNB2 knock-down prior to implantation abrogated tumour initiation and treatment of pre-existing intracranial tumours with Ephrin-B2 blocking antibodies, under conditions that mimic human therapeutic paradigms, strongly reduced the growth and expansion of pre-formed tumours." (PMID 27350048, 2016). "However, sEphB4-Alb treatment leads to fewer tumor blood vessels, suggesting that inhibition of Ephrin-B2/EphB4 pathway may reduce VEGF signaling even though VEGF level is increased." (PMID 21092311, 2010). "Therefore, we hypothesised that despite more vessels being present in the ephrin-B2-overexpressing tumours, these tumours have a decreased functional vascular volume/flow due to inefficient blood supply." (PMID 15083195, 2004). "AP8901 CAR-T cell therapy can specifically recognize and kill EPHB4 receptor-expressing malignant tumor cells by modifying the natural EPHB4 receptor ligand, ephrin B2." (PMID 40842575, 2025). "Co-localization of EphB4/ephrin-B2 with CD34 in stromal microvessels and GFAP in tumor cells has been observed, with higher expression levels in poorly differentiated tumors, reinforcing its relevance to both tumor aggressiveness and vascular pathology." (PMID 41200151, 2025). "To validate the mechanisms through which ephrinB2-Fc-His and Fc-TNYL-RAW-GS reduce local tumor growth and the formation of distant metastases, we repeated hydrodynamic injections of these plasmids and included ephrinB2-Fc (EFNB2-Fc) for comparison." (PMID 39489818, 2025). "In vitro experiments demonstrated that EFNB2, PTTG1IP, and TNFRSF11A were upregulated in dormant tumor cells, which also contributed greatly to the diagnosis of LUAD." (PMID 39273449, 2024). "The results of the present study suggest that an increased level of ephrin-B2, in the presence of a high expression of EFNB2, leads to a more aggressive tumor phenotype." (PMID 39839790, 2024). "To validate the mechanisms through which EFNB2-Fc-His and Fc-TNYL-RAW-GS reduce local tumor growth and the formation of distant metastases, we repeated hydrodynamic injections of these plasmids and included EFNB2-Fc for comparison." (PMID 39091728, 2024). "Concordant with our previous data, EFNB2-Fc, EFNB2-Fc-His, and Fc-TNYL-RAW-GS all significantly reduced local tumor growth while EFNB2-Fc-His was the only treatment that yielded a significant improvement in overall survival." (PMID 39091728, 2024). "Soluble EphB4 binds and sequesters Ephrin-B2 and arrests bidirectional signaling between PI3K-AKT and MAPK, thus exerting an anti-growth effect and attracting immune cells into the tumor." (PMID 38540132, 2024). "LM tumor tissues were digested and cultured, CCK-8 and EdU assays showed that EFNB2 overexpression significantly promoted the proliferation ability of CRC LM cells in vitro." (PMID 36376513, 2023). "To further confirm the expression pattern of EFNB2, we established three types of CRC models, including an orthotopic tumor model, an LM model by spleen injection, and a PM model by tail vein injection." (PMID 36376513, 2023). "LM tumor tissues were digested and cultured, and CCK-8 and EdU assays showed EFNB2 knockdown significantly inhibited the proliferation ability of CRC LM cells in vitro." (PMID 36376513, 2023). "Consistent with the in vitro results, EFNB2 re-expression abrogated the suppressive effects of ITGA5 depletion on xenograft growth, tumor cell proliferation (as assessed by Ki-67 index), and tumor angiogenesis (as assessed by CD31 index)." (PMID 36438491, 2022).
tumor (continued). "A role of TNC-induced ephrin B2 signaling was recently confirmed where, in addition to angiogenesis, the TNC–ephrin B2–EphB4 pathway also promoted tumor cell differentiation into ECs (TDECs), employing NF-κB signaling." (PMID 36102918, 2022). "The mediation effect of EFNB2 on the ITGA5-related regulation of LSCC growth and metastasis was further verified in vivo using a subcutaneous xenograft tumor model and a tail vein lung cancer metastasis mouse model." (PMID 36438491, 2022). "To further define the functional role of EFNB2 in regulation of LSCC progression in vivo, we performed the xenograft tumor formation assay." (PMID 36438491, 2022). "To investigate the role of vascular ephrinB2 and its contribution to HNSCC tumor progression, we used a genetically engineered EFNB2fl/flTie2-Cre-ERT mouse model in which Efnb2 is conditionally knocked out from the endothelial vasculature." (PMID 35725568, 2022). "We have utilised a natural ligand of EPHB4, Ephrin B2, as an antigen recognition site of the CAR molecule, and these CAR‐T cells effectively recognised and eliminated EPHB4‐positive tumor cells." (PMID 34123382, 2021). "Interestingly, immunohistochemical expression of EPHB4 in the venous endothelium and ephrin-B2 in the arterial endothelium was reported greater in tumoral areas compared with non-tumorous ones, possibly underlining the role of the EPH/ephrin system in tumor angiogenesis." (PMID 34445116, 2021). "In this study, EFNA3, EFNB1, EFNB2, and EPHB2 showed a significant correlation with OS and PFS in LUAD patients and were differentially expressed in tumor tissues and normal lung tissues." (PMID 34645436, 2021). "By contrast, SLIT2, EFNB2, FGF9, and HEY1, which promote tumor angiogenesis, were downregulated in 9F-treated HCT116 cells." (PMID 32106543, 2020). "To further assess the role of ephrin-B2–expressing OSCC cells in tumor growth in vivo, we established a tumor mouse model using 5-week-old BALB/c nu/nu mice by subcutaneous injection of SAS-L1 cells into the back of the animals." (PMID 29190834, 2017). "Mechanistically, we found this to be dependent on the upregulation of ephrin-B2 in the GSC themselves, which elicits constitutive activation of Eph forward signalling in the tumour through homotypic cell-cell interactions." (PMID 27350048, 2016). "We next assessed EFNB2 expression in a panel of 8 well-characterised primary human GSC lines isolated from independent patient tumours, including two of the tumours analysed by IHC above." (PMID 27350048, 2016). "A distinctive expression profile of VEGFA, EFNB2, PECAM1/CD31, ANGPT1 and ANGPT2 was revealed: VEGFA, EFNB2, and ANGPT2 were found overexpressed in 84 % to 95 % of tumour samples." (PMID 26044849, 2015). "The specific overexpression of EFNB2 in small tumours with lymphatic spread and the typical decrease of the ANGPT1/ ANGPT2 ratio in larger tumours give weight to EFNB2 and angiopoietins as prognostic factors and potential therapeutic targets." (PMID 26044849, 2015). "Tumours with lymphatic spread showed higher gene expression rates of VEGFA, EFNB2 and ANGPT2 in moderately differentiated tumours and of VEGFA and EFNB2 in small tumours, respectively." (PMID 26044849, 2015). "EFNB2, ANGPT2, and VEGF were overexpressed in 84 % to 98 % of the tumour samples with an average expression factor of 2.3 to 4.5." (PMID 26044849, 2015). "In contrast, in poorly differentiated tumours a higher gene expression of VEGF, EFNB2 and ANGPT2 was observed in tumours with lymphatic spread." (PMID 26044849, 2015). "We previously demonstrated that the low expression of favorable NB genes (EFNB2, EFNB3, EPHB6, NTRK1, CD44 and MIZ-1), as well as that of the tumor growth suppressive gene, EPHA2, in NB cell lines was due to epigenetic silencing." (PMID 24190252, 2014).
tumor (continued). "CD133-positive cells, isolated from the tumor, expressed stem cell markers including nestin, CD133, Ki67, Sox2, EFNB1, EFNB2, EFNB3, Cav-1, Musashi, Nucleostemin, Notch 2, Notch 4, and Pax6." (PMID 22995409, 2012). "Interestingly, elevated levels of ephrin-B2 have been reported in the remodeled blood vessels of tumors that recur after anti-angiogenic treatments and the soluble extracellular domain of EphB4 has been shown to disrupt tumor endothelial cell coverage by mural cells in vivo." (PMID 22194865, 2011). "Cluster I consisted of genes upregulated in CC cells, which included tumor-related genes such as LGR4, AGR2, PCAF, TMEM97, FRAT2, EFNB2 and ZIC2." (PMID 21333016, 2011). "The reduction of the average tumor volume was even more pronounced in sEphB4-Alb treated RT2 Dll4+/- group (approximately 90% reduction, p < 0.01) where Dll4/Notch and Ephrin-B2/EphB4 signaling were simultaneously inhibited." (PMID 21092311, 2010). "sEphB4-Alb mediated inhibition of Ephrin-B2/EphB4 signaling also results in areas of hypoxia in the tumor and increased expression of VEGF and Dll4, which support the combined use of Ephrin-B2, VEGF, and Dll4 inhibitors." (PMID 21092311, 2010). "Similarly, protein and peptide ligands, such as ephrin-B2 and RGD peptides, have been incorporated onto EV surfaces to enhance tumor targeting and improve therapeutic outcomes." (PMID 40284522, 2025). "Notably, targeting the EphB4-ephrinB2 signaling axis with the engineered EphB4 ligands EFNB2-Fc-His and Fc-TNYL-RAW-GS reduces local tumor growth and distant metastasis in a preclinical model of HNSCC." (PMID 39091728, 2024). "EFNB2 expression showed no obvious changes in tumor tissues at different time points in the orthotopic tumor model or the PM model, but was gradually upregulated in tumor tissues at different time points in the LM model." (PMID 36376513, 2023). "Disruption of reverse signaling by transfection with ΔC EFNB2 and ΔC + H EFNB2 showed a comparable metastatic tumor burden with EFNB2 FL, indicating that reverse signaling of EFNB2 was not involve in promoting post-metastatic growth of CRC LM." (PMID 36376513, 2023). "Blocking Ephrin-B2 reverses VEGFR2 signaling and is considered an attractive alternative or combinatorial antiangiogenic therapy strategy for disrupting VEGFR2 function in tumor angiogenesis." (PMID 36910471, 2023). "Ephrin-B2 regulates VEGF signaling by inducing the internalization of VEGFR2 and VEGFR3, thus mediating angiogenesis and lymphangiogenesis in both physiological and tumor conditions." (PMID 36959862, 2023). "The recombinant human erythropoietin competes with ephrin-B2 for binding to EPHB4, and therefore, the tumor progression might be mediated via EPO-induced phosphorylation of EPHB4 and subsequent activation of downstream signaling, independent of the EPOR." (PMID 35694408, 2022). "Ephrin-B2-Fc did not affect neurological symptoms, the number of metastatic loci or metastatic cells, individual and total metastasis volume and tumor cell proliferation." (PMID 34360793, 2021). "Activation of ephrin-B2, through its PDZ domain, has also been shown to control VEGFR2 and VEGFR3 endocytosis and subsequent angiogenic sprouting, lymphangiogenic growth and tumor angiogenesis." (PMID 33634116, 2021). "Human EPHRIN B2 protein was able to bind with both murine EPHB4 and human EPHB4 at a similar level, indicating that our in vivo murine RMS tumor xenograft model may be utilized to ward off any possibility of off-tumor toxicity." (PMID 33816783, 2021). "In particular, it was found that ephrin-B2 is able to control VEGF signalling by inducing VEGFR2 and VEGFR3 internalization, thereby regulating angiogenesis and lymphangiogenesis in physiological conditions as well as during tumor progression." (PMID 31690961, 2020). "Adenoid BCCs were mainly negative for both Ephrin B2 markers except a few cells at the tumour-stroma interaction (TSI) site." (PMID 31065284, 2019).
tumor (continued). "In addition, the growth rate of tumor xenografts and cervical lymph node metastases of OSCC were suppressed by local injection of EFNB2 siRNA." (PMID 29190834, 2017). "This treatment regimen enabled us to assess direct effects of B11 on the tumour cells in the absence of confounding anti-angiogenic effects known to result from ephrin-B2 inhibition." (PMID 27350048, 2016). "In human GBM specimens, high Ephrin-B2 levels were detected in perivascular tumour cells with GSC features at the infiltrative tumour margin, indicative of a role in the GSC compartment in primary tumours." (PMID 27350048, 2016). "Similarly, antibodies that target ephrin-B2 and the extracellular fibronectin type III domains of EphB4 have been shown to modulate angiogenesis and inhibit tumour growth by mechanisms that are still unclear." (PMID 25831049, 2015). "Likewise, we found that ephrin-B2 and CIRBP were expressed at lower levels in malignant tumours compared to benign tumours." (PMID 16969345, 2006). "Increased stromal EFNB2 did not accelerate tumor growth in LNCaPs, similar to BPH1 cells." (PMID 35565468, 2022). "For example, the EphB2 receptor has been presented as a putative tumor suppressor gene in PCa, whereas the EphB4 receptor is known to be both tumor-promoting in the presence of its cognate ligand Ephrin B2 (EFNB2) and a tumor suppressor in the absence of EFNB2." (PMID 35565468, 2022). "Furthermore, we discovered that ephrin-B2 reverse signaling also elicits tumour cell proliferation in the absence of normal anchorage signals by driving Rho-A-dependent cytokinesis in a cell-autonomous manner." (PMID 27350048, 2016). "We found that Hsp90 inhibitors significantly decreased the expression of Ephrin-B2 in multiple KS tumor models (L1T2, SLK-KSHV), which suggests that downregulation of ephrin interactions through Hsp90 inhibitors contributes to their effectiveness in the endothelial lineage tumor KS." (PMID 23209418, 2012). "Additionally, inhibition of the EphB4-ephrin-B2 pathway in experimental HNSCC models led to the reprogramming of the tumor immune microenvironment, suggesting that targeting this system could alter tumor ecology and reduce immune evasion." (PMID 40421081, 2025). "Interestingly, the application of NVP-BHG 712 under endothelial Ephrin-B2 depletion did not result in antimetastatic effects, which might be explained by the missing activation of tumor cell-bound EphB4 in the absence of endothelial Ephrin-B2." (PMID 34360793, 2021). "Moreover, depending on the cell-environment conditions, EphB4 demonstrates the ability to be both a tumor promoter, when over-expressed and in the absence of stimulation by its sole cognate ligand, ephrin-B2, as well as a tumor suppressor stimulated by ephrin-B2." (PMID 25886373, 2015). "Moreover, transient expansion of human PBMC‐derived CAR‐T cells was achieved in the CAR‐T group, and no acute on‐target/off‐tumor toxicity was observed when EPHB4 molecules were targeted by their natural ligand, Ephrin B2." (PMID 34123382, 2021). "In addition, as ephrin-B2 levels are robustly increased in GSC compared to normal neural stem cells and other tissues, such therapies should be relatively tumour-specific and non-toxic." (PMID 27350048, 2016). "Strikingly, quantitative imaging and survival analysis revealed that, while imNSC1 did not form tumours and GSC1 formed tumours at full penetrance, Efnb2 deletion strongly suppressed GSC1 tumour growth and, conversely, Efnb2 overexpression was sufficient to fully transform imNSC." (PMID 27350048, 2016). "Interestingly, under endothelial Ephrin-B2 depletion, the protumorigenic effects of NVP-BHG 712 did not progress, even though we could demonstrate an increased number of proliferating tumor cells." (PMID 34360793, 2021).
cancer (63 papers, 2006 to 2025). A tumor composed of atypical neoplastic, often pleomorphic cells that invade other tissues. "In contrast, a distinct set of female-amplified genes, such as NRXN3 and EFNB2, are linked to the same pathway in comparable cancer types." (PMID 39716176, 2024). "Lastly, ephrin-B2 overexpression in cancer tissues was associated with the clinical stage and low patient OS." (PMID 34445116, 2021). "EFNB2, also known as ephrin-B2, is a transmembrane ligand that can activate Eph receptor tyrosine kinases and has been shown to promote cancer cell proliferation, invasion, and angiogenesis." (PMID 39364872, 2025). "These analyses identified several cancer-related genes, including Kif26a, Acer2, Serpine1, Nr1d2, Efnb2, and Chst11, to be affected by ECS exposure." (PMID 39273313, 2024). "There are also studies reporting a relationship between high EFNB2 expression and decreased survival, making it difficult to make definitive conclusions about the protein’s function in cancer pathology." (PMID 37958393, 2023). "EFNB2, in line with ITGA5, was highly expressed in cancer tissues, compared with normal tissues, and high expression of EFNB2 conferred a poor prognosis in LSCC patients." (PMID 36438491, 2022). "Interaction of EphB4 with its ligand ephrin B2 plays critical roles in both normal development and cancer progression, and in HNSCC, EphB4 is highly expressed in cancer and stromal cells, with lower expression of ephrin B2." (PMID 36175961, 2022). "A plethora of studies have implicated EFNB ligands in cancer cell biology, and several studies report paradoxical effects of EFNB1, EFNB2, and EFNB3 ligands." (PMID 35565468, 2022). "As a cell surface transmembrane ligand for Eph receptors, EFNB2 plays an important role in migration, invasion, and angiogenesis of cancer cells 41-43." (PMID 36438491, 2022). "Ephrin-B2 expression was associated with poor OS and reduced DFS and noted as higher in arterial endothelium of cancer specimens compared with normal ones." (PMID 34445116, 2021). "The coexpression of Ephrin-A3 can block the ability of EphA2 and EphA3 to link ephrins in trans and become activated, while Ephrin-B2 can deter not only EphB4 but also EphA3 in the cancer cells." (PMID 32368295, 2020). "Four of these genes (PCGME1, PEG3, EPHA3, and EFNB2) are of particular interest as they are known to modulate cancer cell proliferation and/or survival." (PMID 28035996, 2016). "Our data demonstrate in malignant tumours a significantly higher expression of VEGF, ANGPT2 and EFNB2 at both, gene and protein levels, in malignant tumours when compared to normal oral mucosa." (PMID 26044849, 2015). "Here we show that in cancer cells, coexpressed ephrin-A3 can inhibit the ability of EphA2 and EphA3 to bind ephrins in trans and become activated, while ephrin-B2 can inhibit not only EphB4 but also EphA3." (PMID 24348920, 2013). "Role of EphB4-ephrin-B2 in androgen deprived mice was tested for role in refractory cancer model." (PMID 40044981, 2025). "Fibroblasts express high ephrin-B2, which activates EphB3/EphB4 in cancer cells." (PMID 38730588, 2024). "Similarly, EFNB2 and EFNB3 are reported to be highly expressed in different types of cancer cells and are associated with poor prognosis." (PMID 35565468, 2022). "Its increased phosphorylation is a driver in EFNB2-dependent cancer development." (PMID 35646067, 2022). "Moreover, EFNB2 had a higher expression level in cancer tissues than in para-carcinoma tissues (p = 0.0458)." (PMID 36052169, 2022). "To date, approaches targeting ephrin-B2 showed potential for cancer treatment." (PMID 29190834, 2017). "Thus, cis interaction with coexpressed ephrin-B2 inhibits EphB4 ligand binding in trans and activation in cancer cells." (PMID 24348920, 2013).